IL10 (interleukin 10)
Diseases named in the same sentence as IL10 in open-access papers (continued):
Sharing a sentence is not in itself a finding about the gene and the disease.
epilepsy (36 papers, 2015 to 2025). A brain disorder characterized by episodes of abnormally increased neuronal discharge resulting in transient episodes of sensory or motor neurological dysfunction, or psychic dysfunction. "Interleukin-10 (IL-10), an anti-inflammatory and neuroprotective cytokine, has been associated with the immunopathology of several diseases, but its role in epilepsy is less studied." (PMID 37025699, 2023). "IL-10, an anti-inflammatory and neuroprotective cytokine, is associated with the immunopathology of several diseases, but its role in epilepsy and its anticonvulsant effects are less studied." (PMID 34215817, 2021). "Recent studies suggest that inflammatory mediators, such as interleukin- (IL-) 1β, IL-6, and IL-10, play a significant role in the underlying pathophysiology of epilepsy, contributing to the onset and perpetuation of seizures." (PMID 33959658, 2021). "When we assessed ASD clinical features solely based on IL-1ß/IL-10 ratios in a larger numbers of subjects, we observed significantly higher frequencies of seizure disorders and antibody deficiency syndrome in ASD subjects with high/low IL-1ß/IL-10 ratios." (PMID 29178897, 2017). "Epilepsy was associated with IL-5 (r = 0.347, P = 0.0020), IL-10 (r = 0.328, P = 0.0036), IL-12p70 (r = 0.370, P = 0.0001), IL-13 (r = 0.346, P = 0.0021), and F2-IsoPs (r = 0.536, P < 0.0001)." (PMID 26236424, 2015). "Genetic testing for IL-10 polymorphisms could become a part of routine evaluation for children with a history of FS or family history suggestive of seizure disorders." (PMID 40832036, 2025). "Therefore, the measurement of plasma IL-10 may have diagnostic value as a biomarker for stratifying TLE + HS from other epilepsy types or as a marker of disease progression towards a progressive form of epilepsy." (PMID 32532251, 2020). "To this end, we analyzed the transcript levels of the inflammasome mediators Il1β, Il6, Il12, Il10, Tnfα, Cd68, Ccl2, and Ccl5, which are upregulated in pilocarpine‐ and kainic acid‐induced epilepsy models." (PMID 40608247, 2025). "Patients with drug‐resistant epilepsy exhibit notably lower average plasma levels of IL‐10, while average serum levels of interferon‐gamma (IFN‐γ) are significantly higher." (PMID 40103702, 2025). "IL‐4 and IL‐10 demonstrate anti‐inflammatory properties inside the central nervous system, thereby inhibiting the development of epilepsy." (PMID 40103702, 2025). "Meanwhile, baicalein and rutin increase anti-inflammatory interleukin-10 (IL-10) levels, thereby mitigating epilepsy." (PMID 39329119, 2024). "In the present study, TNF-α, IFN-γ and IL-6 levels increased in the epilepsy models, while IL-10 and TGF-β2 levels decreased, and these effects were reversed by HsTx2 treatment." (PMID 36457055, 2022). "In the central nervous system, the levels of IL-10 in hippocampus of control group and immune- tolerant group were significantly higher than those in the immune-training group 24 h after epilepsy modeling (P <0.01, P <0.001)." (PMID 35356535, 2022). "Previous findings provide strong support for the involvement of pro-inflammatory cytokines in the pathophysiology of epilepsy with elevated levels of the pro-inflammatory cytokines IL-1β, IL-6, IL-10, IL-17, IFN-α, and TNF-α." (PMID 34791253, 2022). "Another study showed upregulation of IL-10 in the resected hippocampi of epilepsy patients in the areas CA1 and CA3." (PMID 35625063, 2022). "Recent studies show pro-inflammatory cytokines and anti-inflammatory cytokine IL-10 are all involved in the pathogenesis of epilepsy by exacerbating tissue injury, especially in the brain." (PMID 33717768, 2021). "The significance of IL-10 in epilepsy remains controversial because some studies have reported that the level of IL-10 in patients with epilepsy is increased instead of decreased." (PMID 33959658, 2021). "With a strong anti-inflammation effect, IL-10 is known to suppress seizures in epilepsy patients by reducing the expression of interleukin-1." (PMID 33959658, 2021).
epilepsy (continued). "A recent animal study demonstrated that IL-10 inhibits IL-1β production and inflammasome activation in microglia in epileptic seizures, suggesting the potential of IL-10 in the treatment of epilepsy." (PMID 32532251, 2020). "When we compared IL-10 levels only among drug-resistant patients in each epilepsy types, IL-10 levels were still significantly lower in the TLE + HS group than in the TLE-HS group (p = 0.013) and IGE group (p = 0.039)." (PMID 32532251, 2020). "Measurement of the physiological concentrations of IL-10 in healthy subjects would have enabled additional analyses on the impact of our current findings in epilepsy patients." (PMID 32532251, 2020). "More often pro-inflammatory cytokines are found to be elevated in patients with epilepsy, however some researchers report increase of such anti-inflammatory cytokine as IL-10 in patients CSF." (PMID 32403392, 2020). "In epilepsy, specific mechanism by which IL-10 is produced is understudied, probably due to the heterogenous disease pathology." (PMID 32532251, 2020). "A recent report showed that there were unaltered levels of IL-10 among active epilepsy patients with TLE and XLE during the postictal and interictal periods." (PMID 32532251, 2020). "In this study, a bit higher median level of IL-10 is revealed in epilepsy patients with elevated HHV-7 load comparing to the patients without elevated HHV-7 load (p = 0.015), elevated HHV-6 load (p = 0.024) and without roseoloviruses infection (p = 0.013)." (PMID 32403392, 2020). "Therefore, the measurement of plasma IL-10 may have diagnostic value as a potential biomarker for stratifying TLE + HS from other epilepsy types or as a marker for disease progression towards the progressive form of epilepsy." (PMID 32532251, 2020). "In our research, we found that the protein expression of pro-inflammatory factors, including TNF-α, IL-1β, IL-6, and IL-10, was higher in pilocarpine-induced epilepsy." (PMID 31231220, 2019). "Although increased levels of pro-inflammatory cytokines were primarily found in patients with epilepsy, significant elevations of CSF IL-10 were also observed in epileptic patients." (PMID 31312171, 2019). "IL-10 showed significantly lower levels in the “Epilepsy-only” patients compared to the controls and “Cannabis+Epilepsy” (p = 0.0001)." (PMID 31757102, 2019). "The increased IL-10 in epilepsy patients can be due to counteracting mechanisms to the pro-inflammatory stimuli." (PMID 31757102, 2019). "Anti-inflammatory cytokines such as IL-10 and IL-4 are key players in mitigating the detrimental effects of neuroinflammation and may offer therapeutic avenues for preventing or ameliorating epilepsy." (PMID 40723787, 2025). "Consequently, evaluating plasma IL-10 levels can serve as a prospective biomarker/marker to detect the onset of progressive epilepsy." (PMID 39259090, 2024). "A significant increase in proinflammatory cytokines, including IFN-γ, IL-1β, IL-6, IL-10, IL-12, and TNFα, was observed after epileptogenesis, and levels of these inflammatory factors may serve as biomarkers for epilepsy." (PMID 39249163, 2024). "Interleukin-6 and IL-10 concentrations were measured by ELISA in plasma, and the IL-6/IL-10 ratio was calculated in a cross-sectional cohort of 247 patients with epilepsy who had their GADA titers measured previously for their clinical significance in epilepsy." (PMID 37025699, 2023). "Therefore, in this study, we investigated the association of plasma cytokine concentrations of IL-6 and IL-10 and their ratio with GADA in patients with drug-resistant epilepsy." (PMID 37025699, 2023). "Moreover, we made subgroups of patients based on their types of epilepsy, etiologies, and abnormal MRI, and compared the IL-6 and IL-10 levels and their ratio, in different GADA groups." (PMID 37025699, 2023).
epilepsy (continued). "Since IL-1β voided the effect of IL-10 on GABA currents, this supports that the resolution mechanisms of the pathogenic neuroinflammatory response may fail in epilepsy, thus allowing the ictogenic effects of the concurrent inflammatory molecules to prevail." (PMID 36289354, 2022). "This last concept can further explain the controversial contribution of IL-10 in the epilepsy." (PMID 35684043, 2022). "Taking into account the broad anti-inflammatory role of IL-10, an animal study revealed the role of IL-10 in the inhibition of IL-1beta production and inflammasome activation in microglia in response to epileptic seizures, suggesting a role for IL-10 in epilepsy treatment." (PMID 34215817, 2021). "However, the median level of IL-10 was a little higher (p = 0.024, KW) in epilepsy patients with HHV-7 (>10 copies/106 cells) in comparison to epilepsy patients with HHV-6 (>10 copies/106 cells)." (PMID 32403392, 2020). "Interestingly, the anti-inflammatory IL-10 was significantly lower in both epilepsy groups compared to healthy controls; however, it showed a significant higher level in the “Epilepsy + Cannabis” group when compared to the “Epilepsy-only group”." (PMID 31757102, 2019). "It has been hypothesized that the increase of IL-10 in CSF of epilepsy patients can be due to counteracting mechanisms to the pro-inflammatory stimuli." (PMID 31312171, 2019). "Investigation on post-surgery patients with intractable epilepsy revealed increased levels of HMGB1, TLR4, RAGE, NF-κB, p65 and inducible nitric oxide synthase (iNOS) in the brain of the epilepsy group as well as increased levels of IL-1, IL-6, TNF-α, TGF-β, and IL-10 in epilepsy patients." (PMID 30271319, 2018). "Hence, the assessment of plasma IL‐10 could potentially serve as a diagnostic biomarker for distinguishing individuals with TLE and hippocampal sclerosis from those with other forms of epilepsy." (PMID 40103702, 2025). "Therefore, we first carried out a differential gene expression analysis of mRNAs encoding several proteins involved in the IL-10 downstream signaling pathway in GG and TSC patients who underwent surgery for drug-resistant epilepsy and compared with control cortex cases." (PMID 36289354, 2022). "Hence, the reciprocal link between IL-10 and the epilepsy duration should be studied further in a prospective follow-up study to determine whether the IL-10 level could be a marker of disease progression towards the progressive stage." (PMID 32532251, 2020). "In other words, the increased IL-10 tissue expression in the brain, as epilepsy-associated alterations, may not be directly reflected in the systemic circulation." (PMID 32532251, 2020). "We propose the Inflammatory Drug-Resistant Epilepsy Index (IDREI), a novel biomarker derived from plasma concentrations of ICAM-1, IL-4, and IL-10 and CSF levels of NfL, for the prediction of DRE." (PMID 40723787, 2025). "The purpose of this study was to analyses the IL-6 and IL-10 concentrations, including the IL6/IL10 ratio, with regard to GADA titers in the same patient cohort that was previously evaluated for the clinical significance of GAD antibodies in epilepsy." (PMID 37025699, 2023). "Serum α-synuclein did not showed significant correlation with serum levels of IFN-β, IFN-γ, IL-1β, IL-6, IL-10 and TNF-α in patients with epilepsy and acquired demyelinating disorders of the CNS." (PMID 32151248, 2020). "Senescent‐like microglia in aged animals demonstrate elevated transcript levels for a range of SASPs, including IL‐10, IL1B, IL‐6, TNFA, and BDNF, all of which may contribute to epilepsy and seizure vulnerability." (PMID 39031751, 2024). "This study provides fresh evidence that the anti-inflammatory mediator IL-10 affects GABA currents in epileptogenic human tissue, thus bearing implications for novel strategies to increase inhibitory neurotransmission in drug-resistant epilepsy." (PMID 36289354, 2022).
epilepsy (continued). "Compared with children with non-inflammatory neurological diseases like epilepsy, IL-4 was found to be increased in patients with acute and persistent SC and Il-10 and IL-12 were only elevated in patients with acute SC." (PMID 36061386, 2022). "Serum levels of IFN-γ, IL-1β, IL-6 and IL-10 showed negative correlation with age of disease onset in pediatric epilepsy patients, suggesting that younger patients demonstrated higher inflammatory responses to afebrile seizure attacks." (PMID 32151248, 2020). "When analysed, only among refractory patients, as a whole group and groups based on each epilepsy type, IL-10 levels did not correlate with total number of seizures during the month prior to IL-10 analysis (data not shown)." (PMID 32532251, 2020). "Among a small group (n = 15) of non-refractory TLE-HS patients, IL-10 levels showed a moderate negative correlation with the duration of epilepsy (r = − 0.585, p = 0.023)." (PMID 32532251, 2020). "Age, age at disease onset, sex, the frequency of seizures during the month before the labs, the total number of seizures 1 year before the labs and the duration of epilepsy were not correlated with the levels of IL-10." (PMID 32532251, 2020). "The present study assessed the relationship between levels of the soluble cytokines IL-6 and IL-10, including the IL6/IL10 ratio and GADA titers, in patients with DRE in the same population that had GADA titers measured previously to evaluate their clinical significance in epilepsy." (PMID 37025699, 2023). "There is a significant negative correlation between plasma IL-10 levels and the prolongation of seizure time, while the continuous decrease of IL-10 has a significant positive correlation with hippocampal sclerosis in patients with epilepsy." (PMID 33959658, 2021). "Significant difference (p = 0.015, KW) between median levels of IL-10 in samples from epilepsy patients with (>10 copies/106 cells) and without (<10 copies/106 cells) elevated HHV-7 load (34.5, IQR: 21.0–40.3 and 22.0, IQR: 8.5–30.5, respectively) was detected." (PMID 32403392, 2020). "The detection of a negative correlation between IL-10 and the duration of epilepsy may indicate that the production of IL-10 declines concomitantly with the increase in disease duration, regardless of age and gender." (PMID 32532251, 2020). "However, the mechanisms by which IL-10 regulates IL-1β production and inflammasome activation in microglia with epilepsy have not been established." (PMID 30922332, 2019). "However, it is not clear how epilepsy augments inflammasome activation, and what the roles of IL-10 and IL-1β are in the process." (PMID 30922332, 2019). "Interestingly, IL-2 and IL-10 had high variability across all tissues independent of epilepsy status, whereas VEGF, IL-6, and IL-8 showed greater variability in epileptic compared to nonepileptic tissues." (PMID 27737716, 2016). "Moreover, in a study on postictal and interictal phases in active epilepsy patients, neither postictal nor interictal plasma IL-10 changed, suggesting that IL-10 may not exert antiseizure action during this period." (PMID 35684043, 2022). "Elevated concentrations of interleukin-6 (IL-6), interferon-gamma (IFN-γ), and interleukin-17A (IL-17A) have been observed in the plasma during the interictal phase of epilepsy, whereas IL-1β, TNF-α, and IL-10 did not rise in comparison to a healthy group." (PMID 39861097, 2024). "Therefore, taking into consideration the neuroprotective and anticonvulsive effects of IL-10, we performed this study to examine the role of the plasma levels of IL-10 in patients with TLE with HS (TLE + HS), TLE without HS (TLE-HS) and with other types of epilepsy." (PMID 32532251, 2020).
epilepsy (continued). "Therefore, taking into consideration the potential neuroprotective and anticonvulsive effects of IL-10, we performed this study to examine the role of circulating IL-10 in patients with refractory TLE with hippocampal sclerosis (TLE + HS), TLE without HS (TLE-HS) and other epilepsies." (PMID 32532251, 2020).
peritonitis (36 papers, 2011 to 2025). Inflammation of the peritoneum (tissue that lines the abdominal wall and covers most of the organs in the abdomen). "IFN-β can lead to many complex events in bacterial infections, including increased apoptosis, macrophage efferocytosis and resolution of infection in models of Escherichia coli pneumonia and peritonitis, associated with enhanced IL-10 secretion." (PMID 35100872, 2022). "Adoptive transfer of AhR-expressing macrophages protected mice against LPS-induced peritonitis associated with high IL-10 production." (PMID 30283437, 2018). "The lung is frequently affected by systemic inflammation and the development of acute lung injury seems to be associated with local and systemic IL-10 concentrations, examples are hemorrhage, peritonitis, or major surgery." (PMID 22046081, 2012). "The findings demonstrate that the peritoneal administration of both wild-type (WT) and genetically modified adipose-derived mesenchymal stem cells (ASCs) expressing CXCR4 and IL-10 is an effective and safe therapy in this mouse peritonitis model." (PMID 38203690, 2023). "In the mouse model of acute peritonitis, Iripin-1 enhanced the production of the anti-inflammatory cytokine IL-10 and chemokines involved in neutrophil and monocyte recruitment, including MCP-1/CCL2, a potent histamine-releasing factor." (PMID 36756125, 2023). "In murine peritonitis, Dex was found to promote the uptake of apoptotic cells and limit inflammatory cytokine production while enhancing IL-10 secretion." (PMID 36386129, 2022). "The significance of IL-10 and IL-22 upon AhR activation for preventing septic course of S.E.-induced peritonitis has to be elucidated in further studies." (PMID 35203386, 2022). "In the present study, using a murine model of LPS-induced acute peritonitis, we demonstrated administration of IL-10 inhibits inflammatory response via reduction of proinflammatory cytokines, including IL-1β, IL-18, and TNF-α in PLF and serum." (PMID 33414479, 2021). "Using an alum-induced peritonitis model, the induction of the IL-10/STAT3 axis in response to type I IFN and LPS signaling was proposed as a predominant event to explain subsequent immunosuppression." (PMID 32104502, 2020). "Our results showed that the adoptive transfer of high-IL-10-producing macrophages significantly suppressed the inflammatory response, and improved survival in mice with LPS-induced peritonitis." (PMID 30283437, 2018). "Intriguingly, we found that adoptive transfer of AhR-expressing PMs protected mice against LPS-induced peritonitis via increased IL-10-production." (PMID 30283437, 2018). "In a murine peritonitis model, the peak of IL-10 expression in abdominal cavity promotes the differentiation of recruited monocytes towards HLA-DRlow macrophages specialized in apoptotic cells elimination." (PMID 27893741, 2016). "Peritoneal and plasma cytokines (interleukin (IL) 1, tumor necrosis factor α (TNFα), IL-6, IL-10, and interferon γ (IFNγ)) were measured in 66 patients with secondary peritonitis." (PMID 24028733, 2013). "Our results confirm that IL-1, TNFα, IL-6, IL-10 and IFNγ are present at high concentrations in the peritoneal fluid of patients with peritonitis." (PMID 24028733, 2013). "The secretion of the anti-inflammatory cytokine IL-10 by LPS-stimulated peritonitis pMφ was significantly reduced." (PMID 22481867, 2012). "For instance, miR-21 proved to be critical for the production of anti-inflammatory IL-10 in experimental peritonitis, corroborating our findings." (PMID 23093949, 2012). "On the other hand, the ex vivo secretion of the anti-inflammatory IL-10 was decreased in peritonitis macrophages, in line with a pro-inflammatory phenotype." (PMID 22481867, 2012). "In order to check for appropriate cytokine responses to S. aureus, we measured Tnf, Il6, and Il10 levels by Q-PCR in the liver in the peritonitis model." (PMID 21966468, 2011).